CLDN5 (claudin 5)
Diseases named in the same sentence as CLDN5 in open-access papers (continued):
Sharing a sentence is not in itself a finding about the gene and the disease.
renal fibrosis (2 papers, 2022 to 2023). A final common manifestation of a wide variety of chronic kidney diseases characterized by glomerulosclerosis and tubulointerstitial fibrosis. "In the UUO model reduction of renal Claudin-5 and VE-Cadherin was demonstrated to be associated with renal fibrosis progression." (PMID 38235144, 2023). "Here we found that blockade of WIF1 secretion by genetic deletion of Cldn5 or Wif1 in podocytes markedly enhanced renal fibrosis after UUO." (PMID 35332151, 2022).
skin carcinoma (2 papers, 2020 to 2025). "Otherwise, we found claudin-5 overexpression during progression of skin carcinoma associated with EV, which may be related to beta-HPV involvement." (PMID 32518268, 2020). "Cldn5 expression was significantly elevated in malignant cSCC lesions compared to non-malignant flat warts, suggesting Cldn5 may serve as a prognostic biomarker for EpV-associated skin cancer progression." (PMID 40940757, 2025). "In addition, by multivariable analysis, we found a lower chance of negative claudin-5 expression with increasing age, probably associated with the fact that skin carcinoma occurs at an older age, contrary to flat warts, which can appear in childhood." (PMID 32518268, 2020).
subarachnoid hemorrhage (2 papers, 2017 to 2024). A serious neurological disorder characterized by intracranial hemorrhage into the subarachnoid space. "In particular, this type of polyphenol increased the levels of the anti-apoptotic protein Bcl-2 and tight junction proteins such us Zona Occludens 1 (ZO-1), claudin-5, and occludin, after subarachnoid hemorrhage." (PMID 39796474, 2024).
vascular tumors (2 papers, 2020 to 2025). "Claudin-5 has been observed in various carcinomas and other vascular tumors, such as hemangiomas and hemangioendotheliomas." (PMID 40666093, 2025).
abscess (1 paper, 2025). An inflammatory process characterized by the accumulation of pus within a newly formed tissue cavity which is the result of a bacterial, fungal, or parasitic infection or the presence of a foreign body. "Elevated gas pressure increases abscess wall tension, disrupting hepatic sinusoidal endothelial tight junctions (ZO-1 and claudin-5) to create physical conduits for bacterial vascular invasion." (PMID 41048965, 2025).
acute leukemia (1 paper, 2011). A clonal (malignant) hematopoietic disorder with an acute onset, affecting the bone marrow and the peripheral blood. "Our findings suggest that the degradation of tight junction proteins ZO-1, claudin-5 and occludin by MMP-2 and -9 secreted by leukemic cells constitutes an important mechanism in the BBB breakdown which contributes to the invasion of leukemic cells to the CNS in acute leukemia." (PMID 21857898, 2011).
acute pancreatitis (1 paper, 2023). An acute inflammatory process that leads to necrosis of the pancreatic parenchyma. "Furthermore, IL-10 attenuated the increase in BBB permeability and the downregulation of claudin-5 in a rat model of severe acute pancreatitis." (PMID 36882782, 2023).
alternating hemiplegia of childhood (1 paper, 2023). A rare neurodevelopmental disorder characterized by recurrent episodes of hemiplegia and paroxysmal disturbances associated with persistent developmental delay and cognitive impairment. "Very recently, a pathogenic de novo mutation of CLDN5 was originally identified by our group in two independent patients with alternating hemiplegia of childhood (AHC)." (PMID 36978081, 2023).
aneurysm (1 paper, 2025). Bulging or ballooning in an area of an artery secondary to arterial wall weakening. "Serum CLDN3 and CLDN5 levels were measured on days 1, 5, and 9 post-ictus and compared with healthy and aneurysm-bearing controls." (PMID 41114786, 2025).
anxiety disorder (1 paper, 2025). A category of psychiatric disorders which are characterized by anxious feelings or fear often accompanied by physical symptoms associated with anxiety. "This is the first prospective study to examine claudin-5 in PD, a disorder within the anxiety disorder spectrum, where neuronal inflammation is detected in untreated subjects." (PMID 41458033, 2025). "Claudin-5 levels have been examined in many psychiatric disorders other than anxiety disorders." (PMID 41458033, 2025). "However, claudin-5 has not yet been investigated in anxiety disorders." (PMID 41458033, 2025).
atopic dermatitis (1 paper, 2017). "Consistent with our results, the expression of Claudin-5 is decreased in the skin of atopic dermatitis mice." (PMID 28779153, 2017).
Atrophy (1 paper, 2025). Any weakening or degeneration, especially through lack of use. "While chronic suppression of Cldn5 in mice maintained on a cholesterol-enriched diet induced marked RPE atrophy, sustained region-specific knockdown of Cldn5 in the macula of nonhuman primates resulted in RPE degeneration." (PMID 40940757, 2025).
bacterial meningitis (1 paper, 2022). Inflammation of the membranes surrounding the brain and spinal cord due to a bacterial infection. "Downregulation of NEAT1 effectively maintained BBB integrity and decreased BBB permeability in bacterial meningitis experimental models through upregulating miR-135a and downregulating HIF1α to increase the expression of ZO-1, occludin, and claudin-5." (PMID 35346266, 2022). "The enhanced VEGFA expression led to downregulation and altered distribution of tight junction proteins such as ZO-1, occludin, and claudin-5, which eventually increased BBB permeability in bacterial meningitis." (PMID 35346266, 2022).
benign pancreatic tumors (1 paper, 2023). "Additionally, claudin-5 and claudin-7 have great potential in the diagnosis and differentiation of precancerous lesions and benign pancreatic tumors." (PMID 36959784, 2023).
bladder cancers (1 paper, 2017). "Although previous immunohistochemistry studies have shown aberrant expression of claudin-1, -3, -4, and -7 proteins in human tissues of UTUC and bladder cancers, the expression of claudin-5 and its regulatory role in TJ homeostasis during UTUC tumorigenesis still remains elusive." (PMID 28829370, 2017).
brain cancer (1 paper, 2006). A primary or metastatic malignant neoplasm affecting the brain. "In addition, we also observe high correspondence in the two approaches when examining CLDN5 expression, which appears to be especially high in normal brain and brain cancer." (PMID 16836752, 2006).
cavernomas (1 paper, 2020). "However, the tight-junction proteins Claudin-5, and Cingulin, as well as the adherens junction VE-cadherin were not correctly localized at the cell-to-cell contacts in the ECs of the cavernomas of the Pdcd10-ko mice." (PMID 33138917, 2020).
cerebral (1 paper, 2016). "Therefore, the mechanism whereby HS could ameliorate cerebral oedema may be via inhibition of VEGF-mediated down-regulation of ZO-1, and claudin-5 to protect the integrity of BBB." (PMID 27733124, 2016).
cerebral malaria (1 paper, 2024). A sequestration of Plasmodium falciparum in the brain, which can cause coma and/or seizures. "When co-cultured with Pf-iRBC, we show evidence of key features involved in the pathogenesis of human cerebral malaria, including a decrease in TEER, increase in paracellular sodium fluorescein permeability, and disruption of ZO-1, occludin, and claudin-5 localization after 6 h of co-culture." (PMID 38693577, 2024).
cerebral thrombosis (1 paper, 2024). "With CLDN-5 and VE-cad as the potential target proteins of FGFC1, this study provides the regulatory factors for FGFC1 reducing the risk of bleeding transformation following its application in thrombolytic therapy for cerebral thrombosis." (PMID 39195457, 2024). "With CLDN-5 and VE-cad as the potential target proteins of FGFC1, this study provides evidence at the cellular and molecular levels for FGFC1’s reducing the risk of bleeding transformation following its application in thrombolytic therapy for cerebral thrombosis." (PMID 39195457, 2024).
cerebrovascular diseases (1 paper, 2023). "Consistent reduction of tight junction protein, claudin-5 till PD90 in both prenatally e-cig exposed male and female offspring is a serious health concern as it could be associated with long term neurotoxicity and cerebrovascular diseases." (PMID 36899432, 2023).
Chronic colitis (1 paper, 2023). A chronic inflammatory disease of the large intestine (colon, cecum and rectum). "Our research findings demonstrate a positive correlation between the levels of β-hydroxybutyrate in rats with chronic colitis and the tight junction proteins OCLN and CLDN5, with a strong tendency towards a positive correlation with ZO-1." (PMID 37513865, 2023).
chronic kidney disease (1 paper, 2025). Impairment of the renal function secondary to chronic kidney damage persisting for three or more months. "In a chronic kidney disease (CKD) mouse model, elevated systemic urea led to downregulation of Cldn5 in brain endothelial cells, with concomitant disruption of the BBB mediated by MMP2 activation." (PMID 40940757, 2025).
CNS leukemia (1 paper, 2011). "In conclusion, our results established a correlation between MMP-2 and -9 secreted by leukemic cells and the disruption of the TJ proteins ZO-1, claudin-5 and occludin, which increases paracellular permeability of leukemic cell across the BBB in CNS leukemia." (PMID 21857898, 2011).
CO poisoning (1 paper, 2016). "In this study, we investigated the effects of N-butylphthalide (NBP) on the expressions of zonula occludens-1 (ZO-1), claudin-5 and aquaporin-4 (AQP-4) proteins in a CO poisoning rat model." (PMID 27833554, 2016).
colorectal tumors (1 paper, 2023). "It was demonstrated that the aberrant expression of CLDN2, CLDN4, CLDN5, CLDN7, and CLDN23 are associated with the clinical value in colorectal tumors." (PMID 37799140, 2023).
congenital glaucoma (1 paper, 2024). "The gene ontologies for list 7+ linked the non-overlapping genes CDC42EP2, CLDN5, CNN1, DES, KCNMB1, and MYH11 to Congenital Glaucoma." (PMID 39480826, 2024).
Dengue fever (1 paper, 2018). "Likewise, in the setting of Dengue fever, claudin-5 levels correlate with the degree of clinical plasma leakage." (PMID 30259344, 2018).
dermatitis (1 paper, 2022). An inflammatory process affecting the skin. "(L) Quantification of 2000 kDa dextran leakage in the ear skin of control and Cldn5 iECKO mice following Oxazolone-induced dermatitis." (PMID 35861713, 2022). "n≥12 mice, 2 or more fields of view/mouse (M) Quantification of 2000 kDa dextran leakage in the back skin of control and Cldn5 iECKO mice following Oxazolone-induced dermatitis." (PMID 35861713, 2022).
diabetic macular edema (1 paper, 2023). "In support of these findings, a recent study reports abnormal Cldn5 re-distribution leading to anti-VEGF-resistant diabetic macular edema." (PMID 37080089, 2023).
dry age related macular degeneration (1 paper, 2021). Dry age related macular degeneration is characterized by the presence of age-related deposits called drusen and atrophy. "Recent work has found the inner retinal blood vessels to be highly dynamic with claudin-5 expression regulated in a circadian-manner and claudin-5 changes being a key mediator in initiating dry age-related macular degeneration like pathology." (PMID 34867185, 2021).
endometriosis (1 paper, 2021). The growth of functional endometrial tissue in anatomic sites outside the uterine body. "Well in line with the literature, we observed occludin and claudin-5 protein changes in the brain harvested from the endometriosis rats." (PMID 34064310, 2021).
ependymoma (1 paper, 2017). A WHO grade II, slow growing tumor of children and young adults, usually located intraventricularly. "Claudin-5 is displayed in the endothelial cells of the tumor capillaries of the ependymoma tissue (arrowheads)." (PMID 27395057, 2017). "The assessment of claudin-5 expression in ependymoma has the potential to become a useful prognostic marker in this pediatric malignancy." (PMID 27395057, 2017). "Here we show that claudin-5 is highly expressed in the choroid plexus epithelium and in a subset of supratentorial ependymomas." (PMID 27395057, 2017). "Furthermore, we provide data about the influence of claudin-5 expression on overall survival in supratentorial pediatric ependymomas." (PMID 27395057, 2017). "The presence of the tight junction component claudin-5 might contribute to increased cell-cell adhesion between the claudin-5 expressing ependymoma tumor cells and thus interfere with the invasive potential of ependymoma cells." (PMID 27395057, 2017). "However, here we demonstrate that claudin-5 expression by ependymoma cells is a potential predictor of overall survival." (PMID 27395057, 2017). "Importantly, we observed an increased overall survival in claudin-5 expressing supratentorial ependymoma." (PMID 27395057, 2017). "Our observation that a subset of supratentorial ependymomas expresses claudin-5 and displays a different biological behavior may suggest that these ependymomas arise from a distinct progenitor population of the human ventricular system." (PMID 27395057, 2017). "Importantly, in 9 (45 %) of the 20 supratentorial cases the ependymoma tumor cells expressed claudin-5 with appropriate plasma membrane localization." (PMID 27395057, 2017). "Furthermore, we could not detect expression of claudin-1 and −2, occludin or E- and N-cadherin in these cases suggesting that claudin-5 expression delineates a specific subset of ependymoma cases." (PMID 27395057, 2017). "Our data indicates that claudin-5 expressing ependymomas may follow a distinct course of disease." (PMID 27395057, 2017). "Furthermore, in prospective clinical trials with pediatric ependymomas claudin-5 expression should also be registered to evaluate whether this subset of ependymomas displays a different response for adjuvant treatments." (PMID 27395057, 2017). "Surprisingly, we found that 9 out of 20 supratentorial but not infratentorial ependymomas expressed high levels of the brain endothelial tight junction component claudin-5 in tumor cells." (PMID 27395057, 2017). "In our study we confirmed that claudin-5 is expressed by a subset of supratentorial ependymomas and provide evidence that it is not expressed in infratentorial tumors." (PMID 27395057, 2017). "Additionally, we have also analyzed 9 spinal ependymomas and found no claudin-5 expression in the tumor cells (data not shown)." (PMID 27395057, 2017). "Importantly, none of the infratentorial ependymomas showed claudin-5 expression." (PMID 27395057, 2017).
esophageal SCC (1 paper, 2020). "Besides, upregulation of claudin-5 has been associated with prognostic factors, such as risk of metastases in esophageal SCC and cell proliferation and apoptosis in gastric carcinoma." (PMID 32518268, 2020).
fibroids (1 paper, 2023). "Other markers for endometrial receptivity, ER, PR, VEGF-A, integrin αVβ3, and Claudin-5 (CLDN-5) were significantly decreased in patients with fibroids and infertility." (PMID 37108180, 2023).
gastric adenocarcinoma (1 paper, 2023). "Further, CLDN5 immunohistochemical staining was performed using gastric adenocarcinoma tissue microarrays." (PMID 37286335, 2023). "Meanwhile, the differences in CLDN5 expression in gastric adenocarcinoma and paraneoplastic tissues are also consistent with our previous analysis." (PMID 37286335, 2023).
geographic atrophy (1 paper, 2023). "Persistent downregulation of CLDN5 in mice or primates is sufficient to increase retinal vascular permeability and geographic atrophy, suggesting the contributory role of CLDN5 in developing retinopathy." (PMID 37095509, 2023).
glaucoma (1 paper, 2024). Increased pressure in the eyeball due to obstruction of the outflow of aqueous humor. "The mechanics of this is yet to be elucidated though angular aqueous plexus cells are associated with porcine glaucoma and oxidative stress within these cells can lead to upregulation of CLDN5." (PMID 39480826, 2024).
Hepatic fibrosis (1 paper, 2025). The presence of excessive fibrous connective tissue in the liver. "Notably, a reduction in sinusoidal Cldn5 expression correlates with progressive hepatic fibrosis, suggesting that Cldn5 downregulation may contribute to fibrotic remodeling during liver injury." (PMID 40940757, 2025).
Hyperammonemia (1 paper, 2026). An increased concentration of ammonia in the blood. "In an in vitro hyperammonemia model, we found that high ammonia levels significantly increased cell permeability, decreased tight junction protein expression (such as claudin-5) in bEnd.3 endothelial cells, and elevated pro-inflammatory cytokine secretion in C8-D1a astrocytes." (PMID 42222506, 2026).
Hyponatremia (1 paper, 2025). An abnormally decreased sodium concentration in the blood. "Real-time PCR was used to measure mRNA expression levels for claudin-5, occludin, and ZO-1 in the cortex in acute and chronic hyponatremia—induced by either vasopressin or desmopressin." (PMID 40603486, 2025). "There was a significant downregulation of claudin-5 mRNA in AVP-induced acute hyponatremia (p < 0.05, n = 8)." (PMID 40603486, 2025). "In the absence of functional BBB dysfunction, a surprising result was decreased occludin, claudin-5, and zonula occluden-1 gene expression in acute AVP-induced hyponatremia." (PMID 40603486, 2025). "Notably, the decrease in the mRNA level of Claudin-5, a cell-specific marker of endothelial cell tight junction proteins, was significantly reduced in the AVP group in acute hyponatremia." (PMID 40603486, 2025).
hypoxia (1 paper, 2021). A decrease in the amount of oxygen in the body. "Besides, reactive glial cells, members of the NVU, are likely to contribute to the permeability of the BBB observed in cerebral hypoxia through downregulation of paracellular proteins such as Claudin-5 (CLDN5), occludin, and ZO-1." (PMID 34489733, 2021).
in situ carcinoma (1 paper, 2020). A malignant epithelial neoplasm which is confined to the epithelial layer without evidence of further tissue invasion. "In cSCC, we noticed a progressive increase of claudin-5 expression from in situ carcinoma to invasive form." (PMID 32518268, 2020).
kernicterus (1 paper, 2018). A term used pathologically to describe BILIRUBIN staining of the BASAL GANGLIA; BRAIN STEM; and CEREBELLUM and clinically to describe a syndrome associated with HYPERBILIRUBINEMIA. "Claudin-5 is increased in metabolic encephalopathies such as kernicterus." (PMID 30259344, 2018).
kidney transplant (1 paper, 2022). A surgical procedure in which one or both kidneys from a donor are implanted into a recipient. "Immunofluorescent staining of subcutaneous fat biopsies from kidney transplant recipients, and controls, were used to measure microvascular expression of tight-junction proteins (claudin-5, occludin, JAM-1), and control microvasculature for TMAO effects." (PMID 35292710, 2022).
leukodystrophies (1 paper, 2021). "We chose one or more leukodystrophy patient representative of each disease category, and investigated expression of claudin-5, ZO-1, laminin, PDGFRβ, α-dystroglycan and AQP4 together with UEA I and/or GFAP." (PMID 34082828, 2021). "Expression of selective neurovascular unit markers such as claudin-5, zona occludens 1, laminin, PDGFRβ, aquaporin-4 and α-dystroglycan was investigated in eight different leukodystrophies using immunohistochemistry." (PMID 34082828, 2021). "Interestingly, we did not observe abnormalities in the expression of claudin-5 in leukodystrophies, even in those with contrast enhancement." (PMID 34082828, 2021).